ORC1 (origin recognition complex subunit 1)
Diseases named in the same sentence as ORC1 in open-access papers (continued):
Sharing a sentence is not in itself a finding about the gene and the disease.
Caroli disease (1 paper, 2016). Caroli disease (CD) is a rare congenital liver disease characterized by non-obstructive cystic dilatations of the intra-hepatic and rarely extra-hepatic bile ducts. "In this context, we note that ATR-, PCNT- and ORC1-deficient patients display skeletal abnormalities, and there is mounting evidence that cilia function during skeletogenesis, and at least one ATR-SS patient, has been described with multiple liver cysts indicative of Caroli's disease." (PMID 26908596, 2016).
cerebral cavernous malformation (1 paper, 2026). A disorder characterized by malformations in the structure of the capillaries in the brain. "For instance, the Nogo-B receptor (NgBR), expressed on the surface of BECs, modulates the expression of cerebral cavernous malformation (CCM) genes, CCM1 and CCM2, through a HAT from the MYST family, known as histone acetyltransferase binding to ORC1 (HBO1; MYST2)." (PMID 41566325, 2026).
hearing loss (1 paper, 2025). "Then, to further investigate whether RGS8 and ORC1 play a role in age-related hearing loss, we verified the expression of RGS8 and ORC1 in spiral ganglion neurons from different ages of mice." (PMID 40617800, 2025).
lung carcinoma (1 paper, 2023). "The lung cancer dataset showed that the DNA alteration percentages of the ORC complex were 1.9% (ORC1), 1.7% (ORC2), 1.5% (ORC3), 1.2% (ORC4), 2.2% (ORC5), and 1.4% (ORC6)." (PMID 36205357, 2023).
lymph node metastasis (1 paper, 2023). "In our IHC staining results, we found that ORC1/3/4/6 was significantly correlated with recurrence, and ORC1/2/4 was obviously associated with lymph node metastasis in patients with LUAD." (PMID 36205357, 2023).
mastitis (1 paper, 2022). Inflammation of breast tissue during lactation or postpartum due to an obstructed duct or infection. "In this study, the increased gene expression of ORC1, ORC2, ORC4, MCM3, MCM5, and MCM6 in the neutrophils of cows with high SCCs indicated that the cell cycle may be activated in neutrophils in high mastitis risk cows during the transition period." (PMID 35572521, 2022).
medulloblastoma (1 paper, 2017). A malignant, invasive embryonal neoplasm arising from the cerebellum. "Interestingly, here we found that Gmnn levels in human medulloblastomas did not correlate with tumor subtype, histology, or other criteria, but did correlate with elevation of cell cycle related genes, including pre-RC proteins (MCM6, ORC1, and ORC6)." (PMID 29234490, 2017).
melanoma (1 paper, 2022). A malignant, usually aggressive tumor composed of atypical, neoplastic melanocytes. "We have thus assessed ORC1 protein expression by IHC in 28 melanoma tumors from a small cohort of 24 patients treated with ICI, of which 6 patients overlapped with the Ampliseq cohort." (PMID 35892846, 2022). "ORC1 has been shown to be an unfavorable factor in melanoma in agreement with our findings (ORC1." (PMID 35892846, 2022). "However, there is no prior data demonstrating that ORC1 could have a predictive role in therapy with ICI in melanoma." (PMID 35892846, 2022).
osteosarcoma (1 paper, 2023). A usually aggressive malignant bone-forming mesenchymal neoplasm, predominantly affecting adolescents and young adults. "ORC1 was found to control centriole and centrosome reduplication to promote DNA replication in osteosarcoma progression." (PMID 36205357, 2023).
renal cystic disease (1 paper, 2016). "Furthermore, although PCNT and ORC1 deficiency also confer significant defects in cilia signalling, ATR-SS, MOPD-II nor MGS patients show the commonly described manifestations of defective ciliogenesis (e.g. renal cystic disease)." (PMID 26908596, 2016).
retinoblastoma (1 paper, 2020). A malignant tumor that originates in the nuclear layer of the retina. "ORC1 is involved in some critical pathways: Cell Cycle, DNA Replication, E2F transcription factor network, G1 to S cell cycle control, and Retinoblastoma (RB) in cancer." (PMID 32193399, 2020).
tumor (27 papers, 2014 to 2026). "The nuclear staining of MCM2, ‐4, ‐5, ‐10, and ORC1 was positive in 56.79%, 55.56%, 51.85%, 44.44%, and 50.62% of tumor tissues, respectively, and were all positively associated with tumor size, lymph node metastasis, and TNM stage (all p < 0.05)." (PMID 40548893, 2025). "It is well known that the accumulation of genetic mutations is the cause of human cancer, so we analyzed which tumor types occurred ORC1 mutation." (PMID 37833711, 2023). "The expression levels of two protective genes, MRPS7 and ORC1, were higher in normal tissues compared to tumor tissues." (PMID 41942958, 2026). "Strikingly, depletion of MCMs or ORC1 almost completely inhibited tumorigenesis of H358‐ETV4 cells in vivo for 21 days when the average tumor volume derived from the control group reached ≈1000 mm3." (PMID 40548893, 2025). "A novel prognostic risk model based on four CRGs (ORC1, PTTG1, DLAT, PDHB) was developed to stratify COAD patients into high-risk and low-risk groups, assessing overall survival, tumor microenvironment, and mutational landscape differences." (PMID 40276654, 2025). "To determine if MCMs/ORC1 participate in ETV4‐regulated tumor growth in vivo, we stably repressed MCMs/ORC1 in the H358‐ETV4 cells by sh‐MCMs or sh‐ORC1 transfection and double antibiotic‐resistant cell selection." (PMID 40548893, 2025). "We then detected the expression levels of ORC1 in TCGA-PRAD cohort and observed that ORC1 expressed highly in tumor samples versus normal tissues." (PMID 38562999, 2024). "According to the expression level of ORC1, we divided the tumor patients into high-expression Group and low-expression Group, and used TCGA and GEO datasets to study the correlation between ORC1 expression and prognosis of different tumor patients." (PMID 37833711, 2023). "Using the CPTAC Data-set from the UALCAN database, we analyzed the difference of ORC1 phosphorylation levels between normal and tumor tissues at different phosphate sites." (PMID 37833711, 2023). "The expression level of ORC1 in different types of tumor tissues and matched normal tissues were detected by The Cancer Genome Atlas (TCGA) and validated by datasets from the gene expression omnibus (GEO) database." (PMID 37833711, 2023). "The Tide algorithm showed that patients with higher expression of ORC1 had lower T cell dysfunction and higher T cell infiltration into the tumor environment." (PMID 37945594, 2023). "In 3 PDX models from the responder group without BRCA1/2 mutations or BRCA1 promoter methylation, we identified mutations in the DDR genes XRCC3 (HBCx-14), TONSL (HBCx-33) and ORC1 (T302), that were present also in the matched patients’ primary tumours." (PMID 37029129, 2023). "The data further supported that ORC1 expression in tumor tissue was significantly higher than that in normal tissue." (PMID 37833711, 2023). "It was concluded that there were differences between ORC1 and prognosis in different tumor patients, and the relationship between cancer-related fibroblast infiltration." (PMID 37833711, 2023). "ORC1 was one of the 6 common genes expressed correlating with both tumor-specific response, overall clinical response, and PFS in the ICI Ampliseq cohort." (PMID 35892846, 2022). "The knockdown of ORC1 expression suppressed proliferation of tumor cells, which indicated that ORC1 expression is critical to the survival of DLBCL cells." (PMID 34503063, 2021). "Other alternatives include depleting licensing factors like ORC1 to sensitize tumor cells to hydroxyurea and H2O2." (PMID 32854236, 2020). "The oncogene JAK1 contained a high impact mutation within aggressive PET-10 tumor, while high impact mutations were identified in CARD11, NF2 and ORC1 within aggressive PET-20, and in DPY19L2 and SNRPC within non-aggressive PET-24." (PMID 29100308, 2017). "In addition, ETV4 transcriptionally controls the key replisome genes MCM2, ‐4, ‐5, ‐10, and ORC1 expression and affects tumor growth and prognosis of NSCLC patients." (PMID 40548893, 2025).
tumor (continued). "Tazemetostat and Belinostat targeting EZH2 and HDAC simultaneously affect the immunogenicity of GC-DLBC.Inhibition of EZH2 by SHR2554 and HDAC by Chidamide demonstrated combinational anti-tumor action in DLBCL as they lessen DNA replication procedures inclusive of ORC1." (PMID 39951437, 2025). "Lastly, we further established the C4-2B-Enza-R tumor xenograft models and found that ORC1 knockdown could render C4-2B-Enza-R tumors sensitive to enzalutamide treatment, as quantified by tumor volumes and weight." (PMID 38562999, 2024). "In order to explore whether the expression of ORC1 can be used as a prognostic indicator of tumor patients, we analyzed the relationship between the expression level of ORC1 and the overall survival of tumors." (PMID 37833711, 2023). "Finally, in 2 cisplatin sensitive tumours we identify mutations in XRCC3 and ORC1 genes that are functionally validated in vitro." (PMID 37029129, 2023). "This study revealed that ORC1 might inhibit tumor immunity and might be a potential therapeutic target in cancers." (PMID 37833711, 2023). "There were 44 ORC1-expressing cells, of which 32 were tumor cells and 12 were normal." (PMID 37945594, 2023). "Meanwhile it revealed that ORC1 might inhibit the tumor immunity and might be a potential therapeutic target in cancers." (PMID 37833711, 2023). "It was found that the expression of ORC1 in tumor was higher than normal tissue." (PMID 37833711, 2023). "Meanwhile, we verified the difference of ORC1 expression between tumor tissues and adjacent tissues by immunohistochemistry, and found that ORC1 expression was different between tumor tissues and paracancerous tissues, the expression in both UCEC and KICH were higher than adjacent tissue." (PMID 37833711, 2023). "Finally, the expression of ORC1 in tumor tissue and adjacent tissue was verified by immunohistochemistry (IHC)." (PMID 37833711, 2023). "This notion indicated the great efficacy and synergistic anti-proliferative effects in tumor cells which might be attributed to the alternative selectivity profile provided by downregulation of ORC1 expression." (PMID 34503063, 2021). "This is consistent with the previous study that the suppression of cell cycle regulators was accompanied by the down-regulation of a number of genes directly involved in the process of DNA replication (MCM10, ORC1) when tumor cells were subjected to fullerene for 48 h64." (PMID 29795396, 2018). "ORC1 and ORC4 expression was significantly correlated with tumor node metastasis (TNM) stage, lymph node metastasis, and recurrence." (PMID 36205357, 2023). "Results significantly confirmed higher gene expression of ORC1 and CDC6 in tumor cells compared to normal cells." (PMID 37945594, 2023). "Six genes overlapped in the three top 50 lists for tumor response, overall clinical response, and PFS, including MAGOH, C16orf87, ORC1, NAA35, PWP2, and SIAH2." (PMID 35892846, 2022). "The results from qPCR analysis indicated that the combination treatment significantly decreased ORC1 expression in both EZH2 wild-type and mutant tumor cells." (PMID 34503063, 2021). "Validation studies of the expression levels of ORCs in HCC were performed in the GEPIA database, which indicated that ORC1 and ORC3-6 presented high levels of expression in tumor tissues, while ORC2 showed the opposite results." (PMID 32194798, 2020). "In addition, the expression levels of ORC1, TNFRSF12A, TRAF1 and TIAM1 were also positively correlated with tumor grade to a certain extent." (PMID 37005685, 2023).
tumor (continued). "Our results indicated that the expression of ORC1, ORC2, ORC3, ORC4, ORC5, and ORC6 was different in the seven common types of tumor‐infiltrating immune cells, such as B cells, CD4 T cells, CD8 T cells, NK cells, macrophages, endothelial cells, and cancer‐associated fibroblasts." (PMID 36205357, 2023). "Several HBRV CIS are in the vicinity of tumor-suppressor genes, including PTEN, RANBP2, ORC1." (PMID 35632628, 2022).
cancer (23 papers, 2006 to 2025). A tumor composed of atypical neoplastic, often pleomorphic cells that invade other tissues. "This differential expression of ORC1 suggests it has the association with the development of cancer." (PMID 37833711, 2023). "Mapping of origins in cancer cell lines engineered to delete three of the subunits, ORC1, ORC2, or ORC5, shows that specific origins are still used and are mostly at the same sites in the genome as in wild-type cells." (PMID 40530691, 2025). "On the other hand, we have generated cancer cell lines in which one of the ORC subunits, ORC1, ORC2, or ORC5, is mutationally inactivated by CRISPR–Cas9, and the cells are still viable and proliferate with DNA replication." (PMID 40530691, 2025). "Further research is needed to explore ORC1 expression in various cancers and to validate its involvement in cancer cell metabolic reprogramming." (PMID 39795950, 2024). "ORC1 and its co-expression genes were subjected to enrichment analysis to explore potential mechanisms in cancers, and the protein-protein interaction (PPI) network was constructed." (PMID 37833711, 2023). "An analysis of the survival curves of cancer patients found that ORC1 was closely related with poor prognosis in ACC, LIHC, PAAD, READ and THCA." (PMID 37833711, 2023). "Meanwhile, the molecular mechanism of ORC1 in the occurrence and development of cancer was also discussed in multiple aspects." (PMID 37833711, 2023). "When we analysed the cancer-specific genes like Cdc20, Hmmr, Tpx2, Cenpf, Birc5, Ube2c, Foxm1,Pold4, Nup210, Cenpm and Orc1, these pro-carcinogenic genes found to be over expressed in the disease control group." (PMID 36650455, 2023). "We further confirmed the expression of ORCs by IHC staining in LUAD samples and normal lung samples, which showed that ORC1‐6 expression was obviously increased in the cancer tissues of 50 LUAD patients compared with 13 normal lung samples." (PMID 36205357, 2023). "Co-expression network analysis showed that CDCA3, GSG2, KIF2C, NCAPH and PLK1 were positively correlated with ORC1 in cancer, and enrichment analysis showed a correlation with cytosol, ATP binding and cell division." (PMID 37833711, 2023). "This investigation has revealed the significant impact of epigenetic changes following the expression of CDC6 and ORC1, highlighting their potential as novel therapeutic targets in cancer treatment." (PMID 37945594, 2023). "We recognized two novel genes, CDC6 and ORC1, that play crucial roles in cancer development and progression." (PMID 37945594, 2023). "Co-expression network analysis showed that CDCA3, GSG2, KIF2C, NCAPH and PLK1 were positively correlated with ORC1 in cancer, and the functional enrichment mainly included cytosol, ATP binding and cell division." (PMID 37833711, 2023). "However, MYBL2 and ORC1 hadn’t been reported whether associated with cancer stemness." (PMID 34266348, 2021). "There have been already some studies that revealed ORC1 upregulation resulted in DNA re-replication to trigger DNA damage response (DDR) in cancer cells, so some molecule arrested the cell cycle through inducing the accumulation of ORC1." (PMID 30858762, 2019). "For example, it has been reported that ORC1 protein is degraded after entry into S phase in several cancer-derived cell lines." (PMID 17042960, 2006). "Yet, it has been possible to select cancer cell lines that have mutations in Orc1, Orc2, or Orc5 and do not express detectable levels of the proteins and yet load MCM2-7 to the chromatin and replicate their DNA as they proliferate in culture." (PMID 40304571, 2025). "A few human cancer cell lines have been created by CRISPR-Cas9 mediated genome engineering where ORC1, ORC2, and ORC5 cannot be detected by regular immunoblots and yet the cell lines survive, proliferate and replicate DNA with the normal complement of origins of replication." (PMID 40304571, 2025).
cancer (continued). "Finally, to estimate the prevalence of XRCC3 and ORC1 alterations in cancer, we queried the cBioPortal database." (PMID 37029129, 2023). "MCM2 and MCM6 are the upstream transcription factors regulating the ORC1 protein factor and are upregulated in the case of cancer; therefore, it could provide some explanations for the upregulation of ORC1." (PMID 32193399, 2020). "Cancer cells constitutively overexpress replication initiation factors such as ORC1, CDC6, Cdt1, and MCM, so that ORC1 degradation in S phase may be insufficient to fully suppress its function." (PMID 17042960, 2006). "It is also worth noting that in cancer cells in culture, we are seeing a near normal level of loading of MCM2-7 on chromatin when Orc1, Orc2, or Orc5 genes are deleted, and that 60% of the origins of replication remain at the same sites as in WT cells." (PMID 40304571, 2025). "In our eight signature genes (ARL6IP4, ATP2A1, CRYAB, ELFN2, MAP2, MAT1A, ORC1, and POU4F1), prior research has elucidated the expression and function of several genes involved in the initiation and progression of cancer." (PMID 41567198, 2025). "Cancer cell lines in culture can survive and replicate DNA replication after genetic inactivation of individual ORC subunits, ORC1, ORC2, or ORC5." (PMID 40304571, 2025). "These epigenetic modifications play a significant role in influencing the cancer progression following expression of CDC6 and ORC1 in CRC." (PMID 37945594, 2023). "The findings demonstrated that the hub genes ORC1, CDC6, CHEK1, and MAD2L1 promoted the cell cycle checkpoint signaling, which is essential in cancer progression." (PMID 37945594, 2023). "As the result, DNA replication licensing proteins CDT1 and ORC1, two well-known CRL/SCF substrates, accumulate to trigger DNA damage response, leading to G2–M cell cycle arrest, senescence and/or apoptosis in cancer cells." (PMID 32264924, 2020). "Upregulation of ORC1 (origin recognition complex 1), the largest unit of ORC required in the initiation of DNA replication, was gradually confirmed resulting in DNA re-replication to trigger DNA damage response and control cancer cell-cycle." (PMID 34381812, 2021). "Consistent with this idea, we have observed that cell growth is severely inhibited in normal human fibroblasts when ORC1 protein level is reduced by ~80% with shRNA expression while it is not in cancer-derived HeLa cells (own unpublished data)." (PMID 17042960, 2006). "Even in humans, ORC1, ORC2, and ORC5, the essential components of the eukaryotic replication initiation complex, are not essential in some cancer cell lines, suggesting that mechanisms of replication initiation rescue may also operate beyond the bacterial kingdom." (PMID 40439200, 2025).
ORC1 also shares sentences with these, for which no sentence is quoted: Gorlin syndrome (3 papers); dwarfism (2); endometrial cancer (2); Fanconi anemia (2); rectal cancer (2); Adrenocortical carcinoma (1); Bladder Urothelial Carcinoma (1); Breast invasive carcinoma (1); chromophobe renal cell carcinoma (1); colon adenocarcinoma (1); developmental delay (1); diffuse large B-cell lymphoma (1); Intellectual disability (1); intrahepatic cholangiocarcinoma (1); Leukoencephalopathy (1); liver cancer (1); liver cysts (1); lung squamous cell carcinoma (1); Macrocephaly (1); non-small cell lung carcinoma (1); ovarian carcinoma (1); prostate adenocarcinoma (1); rectum adenocarcinoma (1); Sensenbrenner syndrome (1); urea cycle disorder (1); uterine corpus endometrial carcinoma (1); Werner syndrome (1).